PFKFB1 (6-phosphofructo-2-kinase/fructose-2,6-biphosphatase 1)
Description:
Synthesis and degradation of fructose 2,6-bisphosphate.
Synonyms: F6PK; PFRX; HL2K
Tractability: Small molecule: a structure with a bound ligand is known; a high-quality ligand is known; it has a high-quality binding pocket. PROTAC: ubiquitination databases record sites on it; a small molecule that binds it is known.
Target class: Enzyme
Gene: Protein-coding gene on chromosome X (54,931,434 to 54,998,534, reverse strand). Ensembl gene ENSG00000158571.
Pathways (Reactome):
Metabolism: PKA-mediated phosphorylation of key metabolic factors; PP2A-mediated dephosphorylation of key metabolic factors; Regulation of glycolysis by fructose 2,6-bisphosphate metabolism
Gene Ontology:
Molecular function: 6-phosphofructo-2-kinase activity; fructose-2,6-bisphosphate 2-phosphatase activity; identical protein binding; protein binding; ATP binding; catalytic activity
Biological process: fructose 2,6-bisphosphate metabolic process; gluconeogenesis; glycolytic process; positive regulation of glycolytic process; fructose metabolic process; negative regulation of glycolytic process; negative regulation of glycolytic process through fructose-6-phosphate
Cellular component: 6-phosphofructo-2-kinase/fructose-2,6-biphosphatase complex; cytosol
Homologues: Orthologues: chimpanzee PFKFB1 (99% identical), guinea pig PFKFB1 (98% identical), dog PFKFB1 (98% identical), mouse Pfkfb1 (96% identical), rat Pfkfb1 (95% identical), rabbit PFKFB1 (90% identical), macaque PFKFB1 (86% identical), tropical clawed frog pfkfb1 (84% identical), pig PFKFB1 (78% identical), zebrafish pfkfb1 (76% identical), zebrafish si:dkey-96f10.1 (75% identical), Drosophila melanogaster Pfrx (59% identical), and 2 more. Paralogues in human: PFKFB4 (75% identical), PFKFB3 (69% identical), PFKFB2 (68% identical).
Diseases named in the same sentence as PFKFB1 in open-access papers:
PFKFB1 is named in the same sentence as 13 diseases in open-access papers, as found by Europe PMC text mining. Sharing a sentence is not in itself a finding about the gene and the disease. The quoted sentences say what the papers report.
bladder cancer (2 papers, 2020 to 2022). "Using a Cox proportional regression model, we established that a 4-mRNA signature (NUP205, NUPL2, PFKFB1 and PKM) was significantly associated with prognosis in bladder cancer patients." (PMID 32467671, 2020). "Another four-gene glycolytic signature (NUP205, NUPL2, PFKFB1, and PKM) showed excellent performance in predicting the OS of bladder cancer patients." (PMID 35109912, 2022).
diabetes (1 paper, 2013). "The remaining 3 decreased diaphragm carbohydrate metabolism genes, Dcxr, Pfkfb1 and Coq7, were not significantly changed in any previous diabetes studies." (PMID 24199937, 2013).
lung adenocarcinoma (1 paper, 2014). A carcinoma that arises from the lung and is characterized by the presence of malignant glandular epithelial cells. "We then used multiplex RT-PCR and real-time RT-PCR to assess PFKFB1-4 mRNA expression in normal lung tissues and adjacent lung adenocarcinomas from five patients." (PMID 25115398, 2014).
oral cancer (1 paper, 2023). "However, we discovered that PFKFB1 had lower expression in tumor tissues than in normal tissues of patients with oral cancer." (PMID 37919747, 2023).
cancer (11 papers, 2013 to 2025). A tumor composed of atypical neoplastic, often pleomorphic cells that invade other tissues. "PFKFB1 encodes the isoforms that were originally identified in liver, muscle, and fetal tissues, while PFKFB2 encodes the isoforms present in the heart and kidney, and some cancer cells." (PMID 32717953, 2020). "However, using RT-qPCR for further validation, we found that only NUP205 and PKM were upregulated in cancer tissues, and the expression of PFKFB1 in cancer tissues was lower than that in adjacent normal tissues." (PMID 32467671, 2020). "The PFKFB1 gene encodes the isoforms that were originally identified in the liver, muscle and fetal tissue, while the PFKFB2 gene encodes the isoenzyme occurring in the heart and kidney and in some cancer cells." (PMID 30234009, 2018). "However, there has not been a great deal of characterization of the possible role of PFKFB1 in cancer to date." (PMID 24280138, 2013). "Previous studies have shown that the ubiquitous isoform of PFK2/FBPase2 (PFKFB3) localises to the nuclear compartment of cancer cells but the location of the liver isoform of PFK2/FBPase2 (PFKFB1) has not been investigated." (PMID 24566088, 2014). "PFKFB1 has not been well studied and not found to be overexpressed in cancer cells." (PMID 31847435, 2019). "PFKFB1 has not been found to be overexpressed in cancer cells." (PMID 30234009, 2018).
tumor (6 papers, 2019 to 2025). "These PFKFB isoforms were also significantly associated with patient OS, and PFKFB1 was associated with an advanced tumor stage as well." (PMID 31847435, 2019). "Metabolic genes further differentiate prognosis: PFKFB1 expression is elevated in good-prognosis tumours (log2fc = −1.59), reflecting more regulated metabolism compared to aggressive tumours exhibiting metabolic dysregulation." (PMID 41007296, 2025).
bacterial infections (1 paper, 2025). "Pfkfb1, expressed in M2 macrophages, remains poorly understood in the context of intracellular bacterial infections." (PMID 41474810, 2025). "Collectively, these results highlight Pfkfb1 as a critical metabolic regulator that modulates macrophage functionally and orchestrates host antimicrobial defense against bacterial infections." (PMID 41474810, 2025).
infection (1 paper, 2025). The state of being infected such as from the introduction of a foreign agent such as serum, vaccine, antigenic substance or organism. "During infection, Pfkfb1 regulates macrophages metabolic reprogramming to support bacteria proliferation within host cells." (PMID 41474810, 2025). "Infection of WT and Pfkfb1-/- macrophages with pFCcGi-expressing Salmonella mediated a pronounced reduction in bacterial load within Pfkfb1-/- macrophages relative to WT controls." (PMID 41474810, 2025).
PFKFB1 also shares sentences with these, for which no sentence is quoted: multiple myeloma (2 papers); aneuploidy (1); Arthritis (1); Insulin resistance (1); Obesity (1).